ATN1 (atrophin 1)
Description:
Transcriptional corepressor. Recruits NR2E1 to repress transcription. Promotes vascular smooth cell (VSMC) migration and orientation (By similarity). Corepressor of MTG8 transcriptional repression. Has some intrinsic repression activity which is independent of the number of poly-Gln (polyQ) repeats.
Synonyms: D12S755E; DRPLA; B37; CHEDDA; HRS; NOD
Tractability: PROTAC: UniProt records ubiquitination sites on it; ubiquitination databases record sites on it; its protein half-life has been measured.
Gene: Protein-coding gene on chromosome 12 (6,924,463 to 6,942,322, forward strand). Ensembl gene ENSG00000111676.
Subcellular location: Nucleus; Cytoplasm, perinuclear region; Cell junction
Subcellular location (Human Protein Atlas): Nucleoplasm
Pathways (Reactome):
Signal Transduction: Regulation of PTEN gene transcription
Gene Ontology:
Molecular function: protein binding; protein domain specific binding; transcription corepressor activity; transcription coactivator activity
Biological process: negative regulation of transcription by RNA polymerase II; neuron apoptotic process; central nervous system development; cell migration; maintenance of cell polarity; positive regulation of DNA-templated transcription
Cellular component: nuclear matrix; nucleoplasm; nucleus; anchoring junction; cytoplasm; perinuclear region of cytoplasm
Genetic constraint (gnomAD): Loss-of-function variants: 18 observed, 75.9 expected, observed/expected ratio (o/e) 0.24, 90% interval 0.16 to 0.35. The upper end of that interval is the gene's LOEUF score, 0.35, which puts it in group 1 of 6, group 1 being the genes least tolerant of losing a copy. Missense variants: 1,453 observed, 1,534.7 expected, observed/expected ratio (o/e) 0.95, 90% interval 0.91 to 0.99. Synonymous variants: 673 observed, 637.38 expected, observed/expected ratio (o/e) 1.06, 90% interval 0.99 to 1.12.
Gene-disease validity (ClinGen):
ClinGen rates the evidence that ATN1 causes each of these diseases.
dentatorubral-pallidoluysian atrophy (autosomal dominant): Definitive. Dentatorubral pallidoluysian atrophy (DRPLA) is a rare subtype of type I autosomal dominant cerebellar ataxia (ADCA type I; see this term).
Homologues: Orthologues: macaque ATN1 (98% identical), pig ATN1 (95% identical), chimpanzee ATN1 (95% identical), rabbit ATN1 (95% identical), mouse Atn1 (93% identical), dog ATN1 (92% identical), rat Atn1 (88% identical), tropical clawed frog atn1 (50% identical), zebrafish atn1 (33% identical), Drosophila melanogaster Gug (24% identical), Caenorhabditis elegans egl-27 (11% identical). Paralogues in human: RERE (43% identical).
Diseases named in the same sentence as ATN1 in open-access papers:
ATN1 is named in the same sentence as 81 diseases in open-access papers, as found by Europe PMC text mining. Sharing a sentence is not in itself a finding about the gene and the disease. The quoted sentences say what the papers report.
dentatorubral-pallidoluysian atrophy (38 papers, 2006 to 2025). Dentatorubral pallidoluysian atrophy (DRPLA) is a rare subtype of type I autosomal dominant cerebellar ataxia (ADCA type I). "Dentatorubral-pallidoluysian atrophy (DRPLA) is caused by a CAG trinucleotide repeat expansion (≥48 tandem copies) in the Atrophin-1 (ATN1) gene." (PMID 35207493, 2022). "ATN1 is highly expressed in brain tissues and mutations in the ATN1 gene can cause a rare neurodegenerative disease, dentatorubral-pallidoluysian atrophy (DRPLA)." (PMID 32993796, 2020). "Dentatorubral-pallidoluysian atrophy is specific subtype of SCA caused by an expansion of the CAG trinucleotide repeat in the atrophin-1 (ATN1) gene; the number of repeats ranges from 3 to 36 in healthy individuals to 49 to 88 copies in DRPLA patients." (PMID 30283301, 2018). "Further, LSD1 was described as critical for neuronal progenitor cell (NPC) maintenance during cortical development, controlling NPC differentiation by regulating H3K4 methylation of ATN1 (encoding Atrophin 1, a protein related to dentatorubral-pallidoluysian atrophy)." (PMID 34082769, 2021). "Intriguingly, a polyQ expansion of human ATN1 causes dentatorubral pallidoluysian atrophy (DRPLA), a neurodegenerative disease similar to Huntington disease." (PMID 26312756, 2015). "There are two well-documented conditions associated with the ATN1 gene: congenital hypotonia, epilepsy, developmental delay, and digital anomalies (CHEDDA) syndrome and dentatorubral-pallidoluysian atrophy (DRPLA)." (PMID 36660549, 2023). "ATN1 is related to Dentatorubral pallidoluysian atrophy (DRPLA) disease, a rare neurodegenerative disorder, which occurs with the expansion from 7–35 copies to 49–93 copies of a trinucleotide repeat (AAG/CAA)." (PMID 35456240, 2022). "A polyglutamine expansion in ATN1 is responsible for dentatorubral-pallidoluysian atrophy (DRPLA) a progressive disorder of ataxia, myoclonus, epilepsy, intellectual deterioration and dementia." (PMID 28327288, 2017). "ATN1, a gene located on 12p13.31, is a transcriptional regulator and is the cause of the dominant neurological disorder dentatorubral pallidoluysian atrophy (DRPLA) when mutated." (PMID 25329894, 2014). "However, in a fly model of dentatorubral-pallidoluysian atrophy (DRPLA), a disorder caused by mutations in the atrophin-1 protein, autophagy induction was unable to rescue the degenerative phenotype because lysosomal degradation was impaired." (PMID 22518139, 2012). "The ATN1 gene encodes for Atrophin-1 protein, which, as identified in our study, is localized in both the nucleus and cytoplasm of neurons in the human CNS and is associated with DRPLA (Dentatorubral pallidoluysian atrophy)." (PMID 39292690, 2024). "Genes that were part of this signature on the brain side were the TCF4, ATN1, PPP2R2B, ATXN10 and ATXN3, which are associated with neurodegenerative and developmental disorders such as Pitt-Hopkins Syndrome, Dentatorubral pallidoluysian atrophy, SCA12, SCA10 and SCA3." (PMID 27476530, 2016). "We inferred neutral evolution for the three other microsatellites causative of the trinucleotide expansion disorders SCA3 (ATXN3), dentatorubral-pallidoluysian atrophy (DRPLA) (ATN1), and myotonic dystrophy type 1 (DM1) (DMPK)." (PMID 39775235, 2024). "ATN1 is related to dentatorubral-pallidoluysian atrophy (DRPLA), a rare neurodegenerative disorder characterized by cerebellar ataxia, myoclonic epilepsy, choreoathetosis, and dementia." (PMID 36291193, 2022). "Atrophin-1 is reported to be responsible for DRPLA (dentatorubral-pallidoluysian atrophy), a progressive neurodegenerative disorder." (PMID 34006318, 2021). "Using similar structure probing approaches, several “slipped” hairpin variants have been observed for CAG repeats of the atrophin (ATN1), ATXN2, and ATXN3 transcripts, which are implicated in dentatorubral-pallidoluysian atrophy (DRPLA), SCA2 and SCA3, respectively." (PMID 28442996, 2017).
dentatorubral-pallidoluysian atrophy (continued). "Indeed, the Rere protein is able to directly bind the other atrophin paralog ATN1, which is responsible for the neurodegenerative disorder dentatorubral-pallidoluysian atrophy (DRPLA), and to induce its massive re-localization in the nucleus upon overexpression." (PMID 21490719, 2011).
Ataxia (15 papers, 2009 to 2025). Ataxia refers to impaired coordination of voluntary muscle movement. "MAGI2, together with ATN1 (atrophin 1), has been implicated in Dentato-Rubral and PallidoLuysian Atrophy (DRPLA), a disease with a syndrome of myoclonic epilepsy, dementia, ataxia, and choreoathetosis." (PMID 19668339, 2009). "In DRPLA, an abnormal expansion of CAG repeats in atrophin-1 gene causes autosomal dominant hereditary spinocerebellar degeneration, characterized by symptoms such as myoclonus, epilepsy, ataxia, and dementia." (PMID 39364042, 2024).
Huntington disease (15 papers, 2007 to 2025). Huntington disease (HD) is a rare neurodegenerative disorder of the central nervous system characterized by unwanted choreatic movements, behavioral and psychiatric disturbances and dementia. "The exact function of ATN1 is unknown, but an expansion of the trinucleotide repeat within this gene is responsible for dentatorubral–pallidoluysian atrophy (DRPLA), a neurodegenerative disorder similar to Huntington’s disease." (PMID 33294012, 2020).
dementia (7 papers, 2009 to 2024). Loss of intellectual abilities interfering with an individual's social and occupational functions. "Similarly, a girl aged 10 years with intellectual disability was found to have a 99-repeat expansion in ATXN2, despite the fact that both parents were designated as unaffected, and a girl aged 18 years with dementia was found to carry a 69-repeat expansion in ATN1." (PMID 35182509, 2022). "Selected patients with a complex phenotype of movement disorders, dementia, and psychiatric symptoms may be screened for DRPLA (ATN1)." (PMID 35986227, 2023).
spinocerebellar ataxia type 1 (7 papers, 2010 to 2021). Spinocerebellar ataxia type 1 (SCA1) is a subtype of type I autosomal dominant cerebellar ataxia (ADCA type I) characterized by dysarthria, writing difficulties, limb ataxia, and commonly nystagmus and saccadic abnormalities. "For instance, several miRNAs suppress the neurotoxicity of atrophin 1 in spinocerebellar ataxia 1 (SCA1) pathogenesis in a combinatorial manner." (PMID 20920300, 2010).
developmental delay (4 papers, 2023 to 2025). "Besides, de novo variants in both ATN1 and RERE seem to perturb the HX-repeat motif of the atrophin 1 domain, causing congenital anomalies such as hypotonia, epilepsy and developmental delay, which further indicates a link between their functions." (PMID 37845370, 2023).
Machado-Joseph disease (4 papers, 2014 to 2024). "The most frequent SCA worldwide are those caused by CAG repeat expansions, as SCA1 (in ATXN1), DRPLA (ATN1), SCA2 (ATXN2), Machado-Joseph disease (MJD)/ SCA3 (ATXN3), SCA6 (CACNA1A), SCA7 (ATXN7), and SCA17 (TBP), usually designated polyglutamine (polyQ) ataxias." (PMID 39048885, 2024).
schizophrenia (2 papers, 2020 to 2022). A major psychotic disorder characterized by abnormalities in the perception or expression of reality. "Blood brain barrier, brain damage, edema, and headache pathway effects, as well as a potential schizophrenia nodes with connections to MEGF10 and MEGF11 which binds Atrophin 1 (ATN1) a seizure related protein also appear." (PMID 32823271, 2020).
spinocerebellar ataxia type 17 (2 papers, 2022 to 2023). A rare subtype of type I autosomal dominant cerebellar ataxia (ADCA type I). "On the clinical suspicion of an HD phenocopy, we performed analysis of TBP and ATN1, respectively, associated with spinocerebellar ataxia type 17 and dentatorubral‐pallidoluysian atrophy." (PMID 36237940, 2022).
adult T-cell leukemia (1 paper, 2018). "Next, we examined the interaction between CADM1 and CADM4 in cell spreading assay using a cell line, ATN1, which is derived from adult T-cell leukemia (ATL) expressing a high amount of CADM1 protein." (PMID 30131958, 2018).
autism (1 paper, 2017). Persistent deficits in social interaction and communication and interaction as well as a markedly restricted repertoire of activity and interest as well as repetitive patterns of behavior. "Interestingly, humans with trinucleotide expansions within the Atrophin 1 gene, the human Gug homolog, exhibit autism-like behaviors." (PMID 28889104, 2017).
channelopathies (1 paper, 2025). "For example, ATN1 and HTT have been linked to neurodevelopmental disorders, while CACNA1A has been linked to channelopathies with diverse neurological manifestations." (PMID 41254939, 2025).
diabetes mellitus (1 paper, 2016). A metabolic disorder characterized by abnormally high blood sugar levels due to diminished production of insulin or insulin resistance/desensitization. "The two most significant associations identified were for the C6orf10 SNP rs6910071 and “rheumatoid arthritis” (ICD-9 code category 714) (pMETAL = 2.58 x 10−9) and the ATN1 SNP rs2239167 and “diabetes mellitus, type 2” (ICD-9 code category 250) (pMETAL = 6.39 x 10−9)." (PMID 27508393, 2016).
hereditary ataxia (1 paper, 2022). An instance of an atactic disorder that is caused by an inherited genomic modification in an individual. "In patients with suspected hereditary ataxia, we identified expansions in loci that had not been assessed as part of routine diagnostic workup within the NHS at the time of recruitment, including ATN1, ATXN2, ATXN3, ATXN7, CACNA1A, FXN, TBP, and HTT." (PMID 35182509, 2022).
parasitic infection (1 paper, 2023). "Sufficient information on the role of MCM5, ATN1, SCNA and STX1A genes in the context of parasitic infection is not available." (PMID 37761803, 2023).
Rubinstein-Taybi syndrome (1 paper, 2014). A rare malformation syndrome characterized by congenital anomalies (microcephaly, specific facial characteristics, broad thumbs and halluces and postnatal growth retardation), short stature, intellectual disability and behavioral characteristics. "The ATN1 gene located on 12p interacts with CREBBP, a master transcriptional regulator, mutations in which are known to cause Rubinstein Taybi syndrome, no obvious change was noticed in the expression level of CREBBP in the probands' tissue studied (skin fibroblast)." (PMID 25329894, 2014).
neurodegenerative disease (8 papers, 2014 to 2024). A disorder of the central nervous system characterized by gradual and progressive loss of neural tissue and neurologic function. "Although their function is poorly described, mutant alleles of atrophin-1 have been associated with cancer and neurodegenerative disease in humans." (PMID 31253104, 2019). "As shown by the program results DE miR-3687, miR-612, miR-4261, miR-504-3p, miR-126-5p,and miR-411-5p bind to the mRNA of the B3GNT2, CSMD2, ATN1, CREBBP, ATXN1, EMIN4, and EFNA5 genes, which are associated with neurodegenerative diseases." (PMID 39049823, 2024).
cancer (3 papers, 2014 to 2025). A tumor composed of atypical neoplastic, often pleomorphic cells that invade other tissues. "The probability of these six genes to be mutated in normal tissue adjacent to cancer is CPA6 (3.85%), ZNF888 (46.15%), SH3BP1 (76.92%), ANKRD16 (30.77%), ATN1 (11.54%), and C4orf54 (80.77%)." (PMID 40688112, 2025).
ATN1 also shares sentences with these, for which no sentence is quoted: Friedreich ataxia (6 papers); epilepsy (5); amyotrophic lateral sclerosis (4); neurological disorders (4); Alzheimer disease (2); cerebellar ataxia (2); Dystonia (2); fragile X syndrome (2); Huntington disease-like 2 (2); Leber hereditary optic neuropathy (2); mitochondrial disease (2); myoclonic epilepsy (2); Myoclonus (2); myotonic dystrophy type 1 (2); spinal and bulbar muscular atrophy (2); tumor (2); Anxiety (1); autosomal dominant cerebellar ataxia (1); cerebellar degeneration (1); Chorea (1); Choreoathetosis (1); Cognitive impairment (1); colorectal carcinoma (1); Depression (1); developmental and epileptic encephalopathy (1); digital anomalies (1); embryonal carcinoma (1); encephalitis (1); essential tremor (1); frontotemporal dementia (1).
A further 33 diseases each share a sentence with ATN1 in 1 paper.